RNU6-458P (RNA, U6 small nuclear 458, pseudogene)
Gene: Small nuclear RNA gene on chromosome 14 (18,343,038 to 18,343,144, forward strand). Ensembl gene ENSG00000206906.
Homologues: Orthologues: macaque U6 (91% identical), dog U6 (64% identical), rabbit U6 (64% identical), pig U6 (61% identical), rabbit U6 (59% identical). Paralogues in human: U6 (100% identical), U6 (98% identical), RNU6-1293P (97% identical), RNU6-156P (97% identical), RNU6-1132P (95% identical), RNU6-614P (95% identical), RNU6-721P (94% identical), U6 (94% identical), RNU6-978P (93% identical), RNU6-1207P (92% identical), RNU6-811P (92% identical), RNU6-452P (87% identical), and 1289 more.